CTSS (cathepsin S)
Diseases named in the same sentence as CTSS in open-access papers (continued):
Sharing a sentence is not in itself a finding about the gene and the disease.
breast carcinoma (continued). "In conclusion, we have characterised the expression profile of CTSS in breast cancer patient samples and have found that both compartmental and subtype expression of this protease can affect patient outcome." (PMID 31346333, 2019). "In our previous study, we identified CTSS as a gene that is up-regulated specifically in ionizing radiation (IR)-induced rat mammary tumors and that showed that over-expression of CTSS was involved in cellular transformation." (PMID 30006610, 2019). "The high CTSS-expressing mammary tumors (1, 5, 6, and 7) showed low BRCA1 expression, whereas the low CTSS-expressing mammary tumors (2, 3, 4, and 8) showed high BRCA1 expression." (PMID 30006610, 2019). "Both macrophages and tumour cells produce cathepsin S. High expression of cathepsin S in primary tumour samples from breast cancer patients correlates with decreased brain metastasis-free survival." (PMID 28210073, 2017). "CTSs are overexpressed in breast cancer and, as a result, have been suggested to be biological markers for prognosis." (PMID 24932247, 2014). "It is also worth noting that breast cancer was associated with elevated CTSO, pharyngeal and endometrial cancers with elevated CTSS, ovarian cancer with decreased CTSZ, prostate cancer with decreased CTSS, and pancreatic cancer with decreased CTSE." (PMID 38883596, 2024). "Cellular secretion of ICAM1 and CTSS led to the migration and invasion of breast cancer cells." (PMID 36803413, 2023). "In addition, cysteine proteases such as the cathepsin S expressed by breast cancer cells mediate proteolytic cleavage of JAM-B to induce the TEM of breast cancer cells." (PMID 37190188, 2023). "Our present study reported that AQP1 could promote Golgi apparatus extension, leading to increased cell secretion of ICAM1 and CTSS and increasing breast cancer cell migration and invasion." (PMID 36803413, 2023). "Here, we examined the role of CTSS in regulating the DNA damage response in breast cancer cells." (PMID 30006610, 2019). "These are consistent with observations made elsewhere regarding CTSS expression in breast cancer." (PMID 31346333, 2019). "To determine these relationships in human breast cancers, we used human breast cancer tissue arrays and found inverse correlation of expression patterns of CTSS and BRCA1 within each slide, suggesting possibly targeting CTSS to BRCA1 even in human breast cancer tissues." (PMID 30006610, 2019). "Our previous study showed that CTSS was over-expressed in IR-induced rat mammary tumors." (PMID 30006610, 2019). "Previously we have examined the inhibition of CTSS in human astrocytoma and colorectal tumors, but recently Sevenich and colleagues have shown that CTSS inhibition may also have utility in breast cancer." (PMID 27097645, 2016). "Studies using animal models have demonstrated that TAMs are the primary source of high levels of cathepsin B or cathepsin S in prostate, pancreatic islet cancers, and mammary tumors, and its expression by TAMs plays critical roles in multiple stages of tumor growth and metastasis." (PMID 21595995, 2011). "There were 76 proteins detected only in the AQP1-overexpressing group, including proteins reported to exert prosurvival and/or prometastatic activities in breast cancer, such as intercellular adhesion molecule 1 (ICAM1), cathepsin S (CTSS), and PLAT." (PMID 36803413, 2023). "Correlation analysis using 194 IDC patients or the GEPIA database indicated that AQP1 was positively correlated with ANXA2, Rab1b, CTSS, and ICAM1 in breast cancer patients." (PMID 36803413, 2023). "To elucidate the physiological role of CTSS in mammary tumorigenesis, we examined the relationship between CTSS and BRCA1 expression in spontaneously induced rat mammary tumors." (PMID 30006610, 2019). "Tissues of mammary tumors that were spontaneously induced by IR or DMBA and had different BRCA1 expression levels showed an inverse correlation between BRCA1 and CTSS, suggesting that CTSS regulates BRCA1 stability." (PMID 30006610, 2019).
breast carcinoma (continued). "Specifically, the monoclonal antibody Fsn0503, which targets cathepsin S, and the small-molecule cathepsin S inhibitor Z-FL-COCHO were shown to suppress invasion in colorectal, prostate and breast cancer cell lines and to suppress tumor growth in vivo in a colorectal tumor xenograft model." (PMID 30818851, 2019). "However, the clinical utility of CTSS as a biomarker in breast cancer has not been investigated to date." (PMID 31346333, 2019). "Moreover, TAM-derived cathepsins especially cathepsin S and cathepsin B might be one of the mechanisms contributing to TAM-mediated tumor chemoresistance in breast cancer, protecting murine mammary tumor cells from paclitaxel-, doxorubicin-, etoposide-induced cell death." (PMID 39003350, 2024). "Our findings that IRF1 expression contributes to the regulation of RARRES3, GBP4, and CTSS, but not to the regulation of TNFSF10, are further validated by mRNA expression data from breast cancer patients." (PMID 29192143, 2017).
Obesity (32 papers, 2011 to 2025). Accumulation of substantial excess body fat. "Cathepsin S levels are elevated in individuals with type 2 diabetes and obesity, but are reduced after weight loss." (PMID 37627022, 2023). "Studies have also found that the polymorphisms of the CTSS gene are associated with obesity-related traits, and CTSS circulating levels are associated with triglycerides synthesis and accumulation." (PMID 34199180, 2021). "Meanwhile, cathepsin S was found to be involved in the inflammatory process and in diseases such as diabetes, obesity and cancer, and these factors are associated with increased risks of CVD." (PMID 33746900, 2021). "CTSS, encoding for cathepsin S protein, is implicated in body weight regulation and the development of obesity." (PMID 32272881, 2020). "Abnormal expression and/or activity of CTSs have been associated with a variety of human diseases, including inflammatory and cardiovascular diseases, neurodegenerative disorders, diabetes, obesity, cancer, kidney dysfunction, and many others." (PMID 32326609, 2020). "CTSS has been broadly implicated in health and pathology including autoimmune diseases, allergic inflammation and asthma, diabetes and obesity, cardiovascular and pulmonary diseases as well as cancer." (PMID 29622023, 2018). "Given the close link between cathepsin S and various obesity-linked diseases and increased mortality risk, the present results warrant further investigation in further studies." (PMID 25128296, 2014). "In conclusion, we have identified nominally significant associations between several CTSS variants and obesity related parameters." (PMID 22844403, 2012). "Furthermore, CTSS is implicated in osteoimmunological diseases, such as rheumatoid arthritis, as well as in vascular and metabolic complications of obesity, like diabetes mellitus." (PMID 29362520, 2017). "This gene, is coding for the cathepsin-S protein, implicated in vascular and metabolic complication of obesity, which our results suggest might also play a role in CHD protection." (PMID 25951190, 2015). "Furthermore it is increased in adipose tissue and serum of obese persons, whereas studies in obese women have indicated that weight loss by obesity surgery or energy-restricted diet decrease serum cathepsin S." (PMID 25128296, 2014). "Our hypothesis is that common variants in CTSS play a role in body weight regulation and in the development of obesity and that these effects are influenced by dietary factors–increased by high protein, glycemic index and energy diets." (PMID 22844403, 2012). "We addressed this question in a subset of the EPIC cohorts, within the DiOGenes (Diet Obesity and genes) project where both possible associations corresponding to CTSS-SNP main effects and some SNP-dietary interactions (GI, protein intake and energy density) were investigated." (PMID 22844403, 2012). "CTSS variants seem to be nominally associated to obesity related traits and this association may be modified by dietary protein intake." (PMID 22844403, 2012). "However, it remains unknown whether the inhibition of cathepsin S in obesity can reduce cardiovascular risk or improve the metabolic status of obese patients." (PMID 29379789, 2017). "Pioglitazone treatment attenuated obesity-induced elastin fiber fragmentation and elastolytic activity and ameliorated the obesity-induced upregulation of cathepsin S and metalloproteinase 12, predominantly in the PVAT." (PMID 33781257, 2021). "An increasing number of vitro studies, as well as gene analysis, and clinical studies confirmed that Cathepsin S encoded by CTSS in AT is induced by inflammatory factors, which participates in the development of obesity and atherogenesis." (PMID 32684073, 2020). "During chronic inflammatory pathologies, such as obesity or diabetes, a chronic elastolytic activity (e.g., cathepsin S and NE) prevails, which may explain the premature fragmentation of EFs." (PMID 41049496, 2025).
Obesity (continued). "Among these, obesity and the cathepsin S (CatS) enzyme have drawn particular attention." (PMID 41460824, 2025). "Using WGCNA, we confirmed AURKA, ITGB2, CTSS, and TYROBP as hub genes, which were identified in the coexpressed modules in PER♂, whereas AURKA was identified as a hub gene in PER♀, and these hub genes have been associated with obesity comorbidities." (PMID 37458462, 2023). "Cathepsin S has been associated with the pathogenesis of many conditions including but not limited to lung diseases, autoimmune diseases, CVD, type 2 diabetes, obesity, metabolic syndrome, neurodegenerative disease, and cancer." (PMID 35620518, 2022). "Furthermore, it is also remarkable the association of the gene cathepsin S (CTSS), known to degrade several components of the ECM, which is produced by human adipocytes and increased in obesity." (PMID 33803198, 2021). "CTSS gene expression increases with obesity in the adipose tissue of obese rodent and human." (PMID 29966015, 2018). "In addition Cathepsin S belongs to a family of cystein protease that includes other proteases involved in the development of obesity." (PMID 22844403, 2012). "Based on these findings, we hypothesize that genetic variation at the CTSS locus might influence obesity related phenotypes and their variation over time." (PMID 22844403, 2012). "Interestingly, the expression of genes involved in low-grade inflammation associated with obesity such as COX-2 (cyclooxygenase 2), CTSS (cathepsin S), and MMP9 (matrix metalloproteinase-9), which are also AhR target genes, was elevated in obese patients." (PMID 21156398, 2011). "Therefore, it is possible to speculate that dyslipidemia caused by obesity could induce an increase in the expression of GILT, and consequently a defect in lysosomal function by reducing the expression and activity of CTSS." (PMID 34957117, 2021). "The inhibition of CTSs has been widely explored over the last decades in the field of chronic inflammatory diseases, cardiovascular diseases, osteoporosis, arthritis, kidney diseases, pancreatitis, obesity, cancer, neurodegenerative diseases, and many other pathological states." (PMID 32326609, 2020). "In particular, an SFA diet led to an upregulation of genes such as integrin beta 2 (ITGB2), cathepsin S (CTSS), and interleukin-8 (IL-8) in moderately overweight individuals, suggesting that these changes were linked to diet-induced changes rather than obesity." (PMID 29643982, 2018). "Confocal microscopy showed that the expression of CTSS and MMP-12 was upregulated in both aorta and PVAT by obesity but was attenuated by pioglitazone." (PMID 33781257, 2021). "Some of the hub genes identified were AURKA, MELK, and TKT for prenatal LOW vs HIGH nutrition, and CTSS and ITGB2 for late gestation malnutrition followed by early obesity development (LOW-HCHF and HIGH-HCHF vs NORM-CONV)." (PMID 33975549, 2021). "We applied the Attie Lab Diabetes database to verify the hub gene mRNA levels in obesity, which indicated that expression of TYROBP, TLR8, FCER1 G, HCK, NCF2, CTSS and C3AR1 was significantly up-regulated in 10-week obese mice as compared to the lean group." (PMID 32684073, 2020). "PPARγ activation directly upregulated CTSS and MMP-12 expression in the cell types within the PVAT and aorta, accompanied by a reversal of elastin fiber fragmentation and a reduction of elastolytic activity in obesity." (PMID 33781257, 2021). "This study aimed to evaluate the association between obesity, periodontal status, and cathepsin S (CatS) levels in gingival crevicular fluid (GCF) and saliva and assess the impact of obesity on clinical and biochemical outcomes following nonsurgical periodontal therapy (NSPT)." (PMID 41460824, 2025). "While the metabolic phenotype of CTSS−/− mice is currently under investigation, it is not known whether CTSS variants could influence obesity-related phenotypes." (PMID 22844403, 2012).
autoimmune disease (27 papers, 2010 to 2025). A disorder resulting from loss of function or tissue destruction of an organ or multiple organs, arising from humoral or cellular immune responses of the individual to their own tissue constituents. "Cathepsin S has previously been associated with several diseases, such as cancer, cardiovascular disease, autoimmune diseases, and pain, as well as total mortality, and cardiovascular and cancer mortality in older adults." (PMID 38373890, 2024). "Due to its elastase activity, CTSS is crucial in various lung disorders and is implicated in the pathogenesis of numerous inflammatory and autoimmune diseases." (PMID 37727764, 2023). "Dysregulation of CTSS is implicated in multiple autoimmune diseases, including rheumatoid arthritis, systemic lupus erythematosus, multiple sclerosis and SS." (PMID 33562815, 2021). "Due to its distinct role in antigen presentation, CTSS is implicated in autoimmune diseases including rheumatoid arthritis (RA), systemic lupus erythematosus and multiple sclerosis." (PMID 31996771, 2020). "CTSS is implicated in the pathology of other inflammatory and autoimmune diseases such as atherosclerosis, rheumatoid arthritis, multiple sclerosis, bronchial asthma and chronic obstructive pulmonary disease." (PMID 30423938, 2018). "In recent years, CTSS, with its many functions linked to inflammation, has been linked to the etiology of many autoimmune diseases." (PMID 30038391, 2018). "In alignment with its suggested key role in antigen presentation, pharmacologic or genetic inhibition of cathepsin S in preclinical models alleviates pathogenic symptoms in various autoimmune diseases such as multiple sclerosis and arthritis." (PMID 28769925, 2017). "Targeting CTSS has emerged as a therapeutic strategy for autoimmune diseases (e.g., rheumatoid arthritis, asthma, desiccation syndrome, multiple sclerosis) due to its dual role in MHC-II maturation and DC motility." (PMID 40692794, 2025). "Researchers have pursued the clinical development of CTSS inhibitors for decades, with the initial target being autoimmune diseases." (PMID 40794185, 2025). "Its dysregulation drives pathology in autoimmune disorders, chronic inflammation, and neoplasia, establishing CTSS as a multifaceted therapeutic target." (PMID 40692794, 2025). "In keeping with this, the tears of patients with primary and secondary SS contain higher levels of cathepsin S activity compared with healthy individuals or those with other autoimmune diseases." (PMID 36864622, 2023). "Cathepsin S inhibition would therefore be anticipated to have efficacy in CD4+ T cell–mediated autoimmune diseases and amelioration of disease in models of SLE, SS, inflammatory arthritis and multiple sclerosis has been observed." (PMID 36864622, 2023). "We have previously demonstrated that CTSS is elevated specifically in the tears of SS patients relative to patients with other autoimmune diseases or SS-independent dry eye." (PMID 30423938, 2018). "Cathepsin S has been considered a potential therapeutic target in human autoimmune disorders such as MS for over 30 years." (PMID 26075905, 2015). "Our previous report indicated that cathepsin S inhibitor can prevent Sjogren' syndrome which is one of the organ-specific autoimmune diseases found in salivary and lacrimal glands." (PMID 20877570, 2010). "These efforts underscore the expanding applications of CTSS inhibition, from autoimmune diseases (Sjögren’s syndrome) to oncology and vascular remodeling, yet highlight critical challenges in optimizing selectivity and minimizing off-target effects for future candidates." (PMID 40692794, 2025). "The investigators suggest that the inhibition of cathepsin S protects in the progression of lupus nephritis and could be useful in other autoimmune diseases." (PMID 29379789, 2017).
autoimmune disease (continued). "CTSS inhibitors are in phase I and II clinical trials for treatment of autoimmune diseases such as rheumatoid arthritis and SS as well as other diseases associated with extracellular matrix degradation that may have autoimmune components such as abdominal aortic aneurysm." (PMID 31267034, 2019). "CTSS activity is significantly elevated in tears of SS patients compared to tears from patients with non-SS dry eye or other autoimmune diseases." (PMID 33562815, 2021). "Tears from 156 female subjects (33, SS; 33, rheumatoid arthritis; 31, other autoimmune diseases; 35, non-autoimmune dry eye (DE); 24, healthy controls) were analyzed for CTSS activity and Cys C, LF, and sIgA levels." (PMID 30038391, 2018). "Our clinical study has confirmed that CTSS activity is significantly enhanced in SS patient tears relative to tears of patients with other dry eye or non-SS autoimmune diseases." (PMID 28902875, 2017). "CTSS activity was also found to be increased in tears of Sjögren's syndrome patients when compared to patients with other autoimmune diseases, nonautoimmune dry eye, and healthy controls." (PMID 28348600, 2017). "In the present study, tear CatS (CTSS) activity was found to be significantly elevated in the tears of SS patients, compared to healthy controls, and in patients with non-SS related dry eye and other non-SS autoimmune diseases, suggesting its potential as a novel biomarker for SS diagnosis." (PMID 39408709, 2024). "Cystatin C (Cys C), an endogenous inhibitor of CTSS activity, was found to be significantly reduced in the tears of SS patients compared to patients with other autoimmune diseases and non-autoimmune dry eye, which may contribute to the elevated CTSS activity seen in SS tears." (PMID 39408709, 2024). "In addition, CTSS activity is significantly elevated in SS patients tears compared with levels in tears of healthy control subjects or patients with non-SS-related dry eye or non-SS autoimmune diseases, suggesting elevated tear CTSS may uniquely distinguish SS patients." (PMID 31267034, 2019). "The magnitude of the increased CTSS release stimulated by CCh seen in vitro was not of the magnitude seen in vivo in the male NOD mouse (~ 5-fold) compared to BALB/c or in SS patients (~ 40-fold) compared to healthy controls and (~ 4-fold) compared to patients with other autoimmune disease." (PMID 28902875, 2017). "Given that genetic and pharmacological interventions of these CTSs exerted a beneficial effect on autoimmune diseases in model mice, therapy with small CTS inhibitors might help lower the incidence and mortality of ACVD patients with and without autoimmune disease." (PMID 37202785, 2023).